MIR1231 (microRNA 1231)
Synonyms: hsa-mir-1231; MIRN1231
Gene: MicroRNA gene on chromosome 1 (201,808,611 to 201,808,702, forward strand). Ensembl gene ENSG00000221028.
Homologues: Orthologues: chimpanzee MIR1231 (100% identical).